MTOR (mechanistic target of rapamycin kinase)
Diseases named in the same sentence as MTOR in open-access papers (continued):
Sharing a sentence is not in itself a finding about the gene and the disease.
tumor (continued). "Other studies have shown that changes in the activity of the PI3K/AKT/mTOR signaling pathway affect the proliferation of tumor cells." (PMID 37415737, 2023). "We found profound tumor cell destruction under treatment with a combination of Torin 1 (inhibiting mTOR), MK2206 (targeting AKT) and selumetinib (inhibiting MEK) in 3D but not in 2D." (PMID 36675180, 2023). "Through repression of the NOX1/VEGF axis and activation of mTOR and HIF1-α, STK11 loss triggers tumor vascularization." (PMID 37370686, 2023). "Previous studies have indicated that activation of the AMPK/mTOR pathway inhibits the epithelial-mesenchymal transition, repressing tumour cell growth and metastasis." (PMID 37801481, 2023). "Chronic exposure to inflammatory signals present in the tumor microenvironment also contributes to immune cell senescence through the activation of various pathways, including NF-κB and mTOR." (PMID 38075052, 2023). "Proteomics analyses indicate that the nanoparticles reduce the mTOR signaling pathway, which is involved in tumor evolution and reoccurrence, and in the development of metastases." (PMID 37660174, 2023). "The expression of PD-L1 being dependent on the inhibition of mTOR has also been reported in non-tumor cells." (PMID 37834467, 2023). "Their findings were corroborated by studies using genetically engineered mouse models of lung cancer where an mTOR inhibitor, combined with a PD-1 antibody, reduced tumor growth, increased tumor-infiltrating T cells and diminished regulatory T cells." (PMID 36765661, 2023). "First, AMPK inhibits tumor cell proliferation and protein synthesis by negatively regulating mTOR-dependent signaling pathways." (PMID 37180721, 2023). "One avenue through which BCAAs contribute to tumor growth is their transportation into the tumor cell where they can directly activate mammalian target of rapamycin (mTOR) signaling for the tumor’s growth." (PMID 37755304, 2023). "Given that the EGFR/PI3K/AKT/mTOR signaling pathway exerts strong tumor-promoting effects on HCC, it is reasonable to attempt to inhibit this pathway for the treatment of HCC." (PMID 37631344, 2023). "Resistance to cisplatin in NSCLC, achieved through autophagy, is a hindrance and andrographolide is found capable of inhibiting autophagy in cisplatin-resistant NSCLC by activating the Akt/mTOR pathway, and re-sensitizes tumor cells towards cisplatin." (PMID 36986550, 2023). "The well-known PI3K/Akt/mTOR cascade activation has an indispensable role in tumor metabolic activities and intracellular biosynthesis." (PMID 37828561, 2023). "Recently, mammalian target of rapamycin (mTOR) inhibitor revealed an anti-tumor effect in post-transplant recipients with switching regimen, however, there was also reversed opinion about this protective effect." (PMID 36803451, 2023). "Combining mTOR inhibitors with radiation or chemotherapy can enhance the effects of radiation and chemotherapy, sensitizing tumor cells." (PMID 37834408, 2023). "Metformin-induced activation of the AMPK pathway is able to reduce the tumor-promoting activity of insulin and inhibit mTOR, which is closely related to tumor cell proliferation, making metformin an intriguing molecule in cancer therapy." (PMID 37686769, 2023). "Constitutive activation of the PI3K/AKT/mTOR signaling pathway has been identified in MM, leading to uncontrolled tumor growth and survival." (PMID 37190302, 2023). "Using a targeted capture of 577 genes involved in DNA damage response and PI3K/AKT/mTOR pathways, we conducted next-generation sequencing of DNA from matched blood and tumor tissue from 71 HGSC participants." (PMID 36865331, 2023).
tumor (continued). "As the degradation of AR triggers the increase in eIF4E phosphorylation by Mnk1/2, combination of AR antagonists and mTOR inhibitors was effective in suppressing tumor growth." (PMID 36831540, 2023). "PI3K/AKT/mTOR signalling is crucial to various aspects of tumour progression, such as cell proliferation, angiogenesis, tumorigenicity, invasion potential and survival." (PMID 37539493, 2023). "Small‐molecule inhibitors that have been developed and extensively validated for their tumor‐suppressing effects target the PI3K/mTOR pathway." (PMID 37658623, 2023). "4E-BP1 is a tumor suppressor regulating cap-dependent translation that is in turn controlled by mechanistic target of rapamycin (mTOR) or cyclin-dependent kinase 1 (CDK1) phosphorylation." (PMID 37145994, 2023). "In support, findings suggested that Telmisartan inhibited human esophageal adenocarcinoma (EAC) cell proliferation and tumor growth by inducing cell-cycle arrest via the AMPKα/mTOR pathway in EAC cells." (PMID 37891636, 2023). "AZD-2014 promotes autophagy death by blocking the activation of mTOR, thus inhibiting the growth of tumor cells." (PMID 38273841, 2023). "Activation of the PI3K-Akt-mTOR pathway plays a key role in cell viability, resistance against oxidative stress, tumor formation, disease progression, and therapeutic resistance in PCa." (PMID 38201438, 2023). "For example, a suppression of tumor cell proliferation through AKT/mTOR and PI3K/AKT signaling pathways is well known." (PMID 38139235, 2023). "The phosphatase tensin homolog (PTEN) is a tumor suppressor gene that negatively regulates the PI3K/Akt/mTOR pathway." (PMID 37240338, 2023). "Recent studies showed that activation of the LKB1-AMPK- mTOR signaling pathway inhibits the malignant behavior of tumor cells." (PMID 37653482, 2023). "Studies have shown that RAS/PI3K/Akt/mTOR signal transduction axis plays a core role in promoting tumor cell growth, proliferation and survival by inhibiting apoptosis." (PMID 37575275, 2023). "Combining 3BrPA with rapamycin enhanced the anti-tumor efficacy through the dual inhibition of mTOR signaling and glycolysis in LC and neuroblastoma." (PMID 36768924, 2023). "Dysregulated mTOR signalling is frequently observed in HCC and is associated with increased tumour cell proliferation and survival." (PMID 37685919, 2023). "These pathways can be categorized into tumor-related pathways (AKT/mTOR and c-Met) and translation-related pathways (eIF4E release and cap-dependent mRNA activation factors)." (PMID 38072995, 2023). "Subsequent treatment modalities included surgical resection of metastases, radiotherapy, tumor embolization, as well as systemic treatment including immunotherapy, chemotherapy, and treatment with mTOR- or tyrosine kinase inhibitors (TKIs)." (PMID 38136261, 2023). "Since Akt/mTOR signaling stimulation supports tumor development by regulating cell growth 33, we examined the functional consequence of CTSG absence-mediated activation of Akt/mTOR action." (PMID 37151875, 2023). "The dual inhibition of mTOR and glycolysis synergistically passivates the proliferation and tumor development of mTOR hyperactive cells." (PMID 37853445, 2023). "In summary, targeting the EGFR/PI3K/AKT/mTOR signaling pathway via the inhibition of EGFR, PI3K, AKT, and/or mTOR has consistently shown anti-tumor effects on HCC cells in vitro." (PMID 37631344, 2023). "PI3K/AKT and downstream molecule mTOR can promote tumor proliferation, survival, metastasis, and invasion, and inhibit autophagy and senescence." (PMID 36980736, 2023). "The PI3K/AKT/mTOR signaling pathway has emerged as a critical player in the regulation of tumor immune microenvironment." (PMID 37152048, 2023). "In vitro experiments showed that the knockdown of WDR45B can suppress autophagy by upregulating the Akt/mTOR signaling pathway and reduce tumor proliferation and migration." (PMID 36900050, 2023).
tumor (continued). "Although a variety of targeted molecular inhibitors can exert potential anti-tumor effects through the PI3K/AKT/mTOR pathway, to date, the clinical efficacy of these inhibitors as a monotherapy has shown meager response rates." (PMID 38008753, 2023). "Among these miRNA-mRNA pairing, tumor suppressive miR-99b-5p negatively regulates MTOR expression (at mRNA and protein levels) and play a central role in regulating PI3K/AKT/mTOR/HIF-1α/VEGF signaling axis." (PMID 38023145, 2023). "Dysregulation of the mTOR signaling pathway disrupts cellular homeostasis, leading to severe consequences such as malignant transformation, tumor formation, autophagy, and ultimately human diseases." (PMID 38288086, 2023). "In fact, mTOR inhibitors are widely applied in different solid cancers due to their anti-tumor activity, combined with a TCB that targets solid tumors, which seems to be a way to prevent the occurrence of CRS while retaining its efficacy." (PMID 36701037, 2023). "Some researchers associate decreased CA9 expression in patients with poor prognosis with the activation of AKT and mTOR pathways, which makes further tumor growth less dependent on hypoxia and shifts it to an alternative pathway." (PMID 37443682, 2023). "The finding that numerous tumors manifest abnormal mTOR expression led to its potential inhibition as a novel anti-tumor strategy." (PMID 38201496, 2023). "The dual inhibitors of metabolic pathways can have a better effect in preventing the growth and progression of tumor cells due to the simultaneous inhibition of pathways such as the PI3K/AKT/mTOR pathway." (PMID 37046703, 2023). "Fourth, 58.3% (n = 35) of all analyzed mTOR-positive tumor samples are derived from patients with FIGO I tumor stage." (PMID 37623437, 2023). "Altogether, these findings suggest that NaB regulates tumor activity by inhibiting the activation of the mTOR pathway and promoting ferroptosis." (PMID 37185889, 2023). "Mechanistically, TTK was found to regulate the proliferation and apoptosis of tumor cells through the Akt-mTOR pathway, where TTK knockdown inhibited its activation." (PMID 37770979, 2023). "The inhibition of AKT and mTOR expression can negatively control the activity of enzymes related to the glycolytic pathway and angiogenesis in tumour cells." (PMID 37156724, 2023). "KRASKRAS belonging to the RAS family, is one of the most prominent proto-oncogenes, and associated with various oncogenic pathways including PI3K/AKT/mTOR signaling to promote proliferation and to suppress apoptosis of tumor cells." (PMID 37927787, 2023). "MOB1A plays a role in promoting the malignant biological behavior of tumor cells through PI3K/AKT/mTOR signaling pathway." (PMID 37314589, 2023). "Mutations in this axis promote the overactivation of the PI3K/AKT/mTOR signaling cascade or the inhibition of the tumor suppressor PTEN." (PMID 37887570, 2023). "AMPK is activated when energy is depleted, accounting for the inactivation of mTOR and tumor cell growth inhibition." (PMID 37180721, 2023). "REDD1-deficient TAMs exhibited highly glycolytic features and increased glucose uptake in an mTOR-dependent manner, which impinges on neovascularization and tumor metastasis; however, the tumor growth remains unaffected." (PMID 37740232, 2023). "Due to its unique dosage form, nab-sirolimus has a superior pharmacokinetics profile, higher tumour tissue drug exposure, stronger target cell inhibition, and better safety profile than other marketed mTOR inhibitors." (PMID 37489050, 2023). "Our recent study shows that ONC201 or ONC206 effectively inhibits tumor cell proliferation and tumor growth through inhibition of the Akt/mTOR pathway in EC cell lines and a transgenic mouse model of EC28–31." (PMID 37069726, 2023). "Among others, it is known to inhibit tumor growth by remodeling the tumor-immune microenvironment involving changes in macrophage polarization and facilitating the mTOR-mediated reprogramming of glucose metabolism." (PMID 36839769, 2023).
tumor (continued). "Increased PI3K/AKT/mTOR signaling activity in stroma/immune cells surrounding the tumor cells further validates the role of genomic-independent mechanisms within the tumor microenvironment as key regulators of the PI3K/AKT/mTOR signaling cascade." (PMID 36797347, 2023). "Mammalian targets of rapamycin (mTOR) in cancer cells can regulate protein translation and participate in the regulation of tumor cell growth and autophagy." (PMID 38139250, 2023). "The coactivation of autophagy and mTOR signaling pathways is mutually dependent on the regulation of the metabolism of tumor cells." (PMID 36906611, 2023). "PI3K/AKT/mTOR pathway is a crucial axis in regulation of various pathophysiological cellular processes such as cell proliferation, metabolism, and tumor progression." (PMID 37596669, 2023). "Several oncogenic signaling pathways, including Src/STAT3, EGFR, HER2, MAPK, AKT/mTOR, WNT/-catenin and miRNA-related pathways, have been associated with changes in tumor cell surface CD24 expression." (PMID 37846296, 2023). "Conversely, rapamycin and sirolimus, Mammalian Target Of Rapamycin (mTOR) inhibitors, have been reported to prevent tumor growth and progression in animal models." (PMID 37511937, 2023). "Gene set enrichment analysis (GSEA) of the TCGA dataset and two other GEO cohorts also revealed that the gene sets related to MAPK and mTOR/AKT signaling pathways were enriched in tumor samples with high PDE4DIP expression." (PMID 37355626, 2023). "Our study found that some important pathways that affect tumor development, such as mTOR, angiogenesis, and epithelial-mesenchymal transition, predicted poor tumor immunotherapy outcomes." (PMID 38093298, 2023). "GALNS is overexpressed in NPC tissues, and promotes tumor growth via the PI3K/AKT/mTOR signaling pathway." (PMID 37707658, 2023). "Metformin has been suggested to be a direct tumour growth inhibitor by downstream suppression of signalling through mTOR." (PMID 37834839, 2023). "GCDC promotes AMPK expression to inhibit mTOR signaling, leading to induction of autophagy and increased tumor cell invasion." (PMID 36759819, 2023). "Combining mTOR inhibitors with conventional chemotherapeutic agents like temozolomide has synergistic effects, leading to increased tumor cell death and improved sensitivity to chemotherapy." (PMID 37834408, 2023). "It was revealed in this study that ESM1 promoted angiogenesis in CRC by activating the PI3K/Akt/mTOR pathway, thus accelerating tumor progression, consistent with previous studies." (PMID 37100467, 2023). "To summarize, the PI3K/AKT/mTOR pathway promotes tumor cell proliferation, migration, and angiogenesis." (PMID 37070074, 2023). "In MB, a mutated mTOR pathway leads to increased IDO1 expression, which triggers the expansion of regulatory T cells enabling tumor cells to grow." (PMID 37509316, 2023). "Our study showed that the expression intensity of p-AKT, p-PI3K, and p-mTOR decreased in SH-SY5Y tumor tissues obtained from nude mice both in monotherapy groups (monensin alone, rapamycin alone) and in combination therapy groups." (PMID 37370314, 2023). "Liposomes for the co-delivery of honokiol and disulfiram/copper complex were developed to explore anti-GBM therapy via the mTOR regulatory pathway to remodel tumor metabolism and the tumor immune microenvironment." (PMID 37273792, 2023).
tumor (continued). "Dysregulated PI3K/AKT/mTOR signals are responsible for tumorigenesis via inducing tumor growth, metastasis, and resistance to antitumor therapies in glioblastoma." (PMID 37046703, 2023). "Rapamycin or rapalog drug is an autophagic inducer that promotes tumor survival in TSC mouse models through inhibiting mTOR pathway." (PMID 36760166, 2023). "Previous reports indicate that autophagy is regulated by the PI3K/AKT/mTOR signaling pathway to regulate tumor migration, invasion, and proliferation." (PMID 37415741, 2023). "Under hypoxic conditions, HIF1A expression increases and induces downstream signal pathways, and PI3K -Akt-mTOR signaling pathway can promote tumor proliferation." (PMID 37081097, 2023). "Activation of PI3K/AKT/mTOR will increase drug resistance of colorectal cancer cells, inhibits apoptosis, and promotes tumor cells survival." (PMID 38273841, 2023). "This tumor suppressor complex inhibits the activation of mTOR, which is a fundamental regulatory kinase in cell growth, cell division, motility, survival, protein synthesis, and transcription." (PMID 36703202, 2023). "In summary, these observations suggest that the combination of vinorelbine with mTOR inhibitors effectively slowed tumor growth by promoting apoptosis, enhancing vascular function, and decreasing tumor hypoxia." (PMID 38203186, 2023). "The proposed mechanism of anti-tumour adenine activity includes activation of the AMPK/mTOR signalling pathway, which induces autophagic cell death." (PMID 36774883, 2023). "Rapamycin, an mTOR inhibitor, was developed to inhibit proliferation signals in the PI3K/AKT/mTOR pathway, which is important for cell growth and proliferation in multiple tumour types (Ref." (PMID 36994671, 2023). "Among others, we found significant enrichment in glycolysis, hypoxia, and mTOR signaling in the “Greenyellow” module (arrowheads), indicating that the tumor cells in qMCP−/−; Ntv-a mice are likely experiencing higher metabolic stress." (PMID 37012245, 2023). "AKT phosphorylates several substrates and downstream effectors, including mTOR, matrix metalloproteinase (MMP), cyclin-dependent kinases (CDKs), and VEGF, associated with tumor progression and metastasis." (PMID 37511127, 2023). "BFAL1 serves as a ceRNA to sponge miR-155-5p and miR-200a-3p and regulates the expression of RHEB, activates the RHEB/mTOR signaling pathway, and promotes tumor growth." (PMID 37280524, 2023). "PI3K/Akt/mTOR signaling plays important roles in promoting tumor initiation, progression and therapy responses." (PMID 38136311, 2023). "Recently, CUDC-907 has been demonstrated to inhibit both HDAC1 and HDAC2 as well as PI3K, Akt and mTOR expression and this resulted in an inhibition of NB tumor growth in a 3D spheroid tumor model." (PMID 37679770, 2023). "An mTOR inhibitor decreased the survival and suppressed the invasion of colorectal CSCs in vitro, and suppressed tumor growth in vivo." (PMID 37490168, 2023). "From animal experiments, when LncTUG1 was knocked down, miR-144-3p increases while the expression of RRAGD, mTOR and S6K reduced in neoplasm tissues, and the neoplasm volume is also reduced." (PMID 37160972, 2023). "The expression levels of apoptosis-related proteins and PI3K/Akt/mTOR pathway proteins in the tumor tissues of the control group and the piperine-administered group were confirmed by western blot assay." (PMID 37762259, 2023). "4EBP1 activity is controlled by the evolutionary conserved kinase, mammalian target of rapamycin (mTOR) and abnormal activity of this regulatory circuit is characteristic of tumor cells." (PMID 37386121, 2023).